SLURP1 (secreted LY6/PLAUR domain containing 1)
Diseases named in the same sentence as SLURP1 in open-access papers (continued):
Sharing a sentence is not in itself a finding about the gene and the disease.
epidermoid carcinoma (2 papers, 2023). "Here, we confirmed the association of SLURP-1 antiproliferative effect in epidermoid carcinoma A431 cells with α7-nAChR and showed its dependence on mitogenic signaling pathways, Src family kinases and STAT transcription factors." (PMID 37854069, 2023). "Here, we investigated the molecular mechanisms underlying SLURP-1 activity in A431 cells in vitro and studied the activity of the protein and 21 a.a. peptide mimicking its loop I (named “Oncotag”) in vivo in a xenograft mice model of epidermoid carcinoma." (PMID 37854069, 2023). "Intravenous injection of a synthetic peptide mimicking SLURP-1’s loop I (Oncotag) suppressed tumor growth and metastasis in a xenograft mice model of epidermoid carcinoma in a similar way to rSLURP-1." (PMID 38069271, 2023). "To study the antitumor effect of SLURP-1 and Oncotag in vivo, we used xenograft mice model of human epidermoid carcinoma." (PMID 37854069, 2023). "One hour incubation of human epidermoid carcinoma A431 cells with recombinant SLURP-1 induces secretion of endogenous SLURP-1 from an intracellular depot, thus increasing the SLURP-1 concentration in extracellular media and overall antiproliferative effect." (PMID 37854069, 2023). "Here, we investigated mechanisms of antiproliferative activity of recombinant SLURP-1 in epidermoid carcinoma A431 cells and activity of SLURP-1 and synthetic 21 a.a. peptide mimicking its loop I (Oncotag) in a xenograft mice model of epidermoid carcinoma." (PMID 37854069, 2023).
Hyperkeratosis (2 papers, 2019 to 2024). Hyperkeratosis is a histopathological term defining a thickened stratum corneum and may be present in many different skin conditions, with many possible overlaps. "Therefore, when SLURP1 is non-functional, as seen in Mal de Meleda, severe hyperkeratosis results due to improper keratinocyte apoptosis regulation." (PMID 31443639, 2019).
lung adenocarcinoma (2 papers, 2021 to 2023). A carcinoma that arises from the lung and is characterized by the presence of malignant glandular epithelial cells. "SLURP-1 controls growth and migration of lung adenocarcinoma A549 cells via interaction with α7-nAChR heterocomplexes with EGFR or PDGFR and modulation of the PI3K/AKT/mTOR and inositol-1,4,5-trisphosphate (IP3) pathways." (PMID 37854069, 2023). "We have previously shown that SLURP-1 inhibits migration of lung adenocarcinoma A549 cells via interaction with α7-nAChR/EGFR/PDGFR complexes, while the anti-migration activity of Oncotag in A549 cells depends solely on interaction with α7-nAChR." (PMID 37854069, 2023). "Previously we showed, that a recombinant analogue of human SLURP-1 (rSLURP-1) diminishes the lung adenocarcinoma A549 cell proliferation and abolishes the nicotine-induced growth stimulation." (PMID 34595181, 2021).
Pruritus (2 papers, 2011 to 2016). Pruritus is an itch or a sensation that makes a person want to scratch. "Whether SLURP1 is over-expressed in patients with pruritus or under-expressed in the Wilson patient cannot be derived from our data." (PMID 21779339, 2011). "SLURP1 was elevated in 9 of the 11 patients with pruritus (82%) and in 7 of the 12 patients without pruritus (58%), but in none of the four patients with pruritus who were treated with rifampicin." (PMID 21779339, 2011). "This subgroup showed lower levels of SLURP1 than the group of patients with pruritus who were not receiving the drug." (PMID 21779339, 2011).
Allergy (1 paper, 2021). An allergy is an immune response or reaction to substances that are usually not harmful. "For one, the previously published suggestive evidence for an anti-inflammatory effect of SLURP-1 in skin disease and allergy was strong." (PMID 33815383, 2021).
benign prostatic hyperplasia (1 paper, 2024). A non-cancerous nodular enlargement of the prostate gland. "Currently, there is a lack of reported data regarding the expression of SLURP1 in benign prostatic hyperplasia (BPH) and PCa, leaving uncertainty regarding its viability as a diagnostic marker for PCa." (PMID 38686195, 2024).
bladder tumor (1 paper, 2025). "Our findings suggest that SLURP1 and LY6D together may promote bladder tumor growth and progression via mechanisms involving immune evasion, antioxidant stress responses, and anti-apoptosis." (PMID 40740240, 2025).
cervical cancer (1 paper, 2014). A primary or metastatic malignant neoplasm involving the cervix. "Therefore, it was believed that SLURP1 and SYDE2 were potential therapeutic targets for cervical cancer." (PMID 25109897, 2014). "SLURP1 and SYDE2 may be potential therapeutic targets for cervical cancer." (PMID 25109897, 2014). "Furthermore, SLURP1 and SYDE2 may be potential therapeutic targets for cervical cancer." (PMID 25109897, 2014).
cholestasis (1 paper, 2011). Impairment of the bile flow caused by obstruction within the liver, or outside the liver in the bile duct system. "In this respect, we have shown that SLURP1, one of the proteins removed by MARS from patients' blood, is overrepresented in serum from patients with cholestasis." (PMID 21779339, 2011).
chronic pancreatitis (1 paper, 2018). A chronic inflammatory process causing damage and fibrosis of the pancreatic parenchyma. "We detected similar levels of SLURP1 in sera from healthy donors and patients with chronic pancreatitis or PDAC; higher preoperative values were associated with significantly better survival in patients with resected tumors." (PMID 29545933, 2018).
E. coli infection (1 paper, 2021). "Together, these results revealed that E. coli infection could induce SLURP1 secretion." (PMID 34721415, 2021).
endometriosis (1 paper, 2017). The growth of functional endometrial tissue in anatomic sites outside the uterine body. "In cervical mucus of patients with endometriosis we reported the absence of the scavenger proteins SLURP-1 and SLURP-3." (PMID 28174513, 2017).
eosinophilia (1 paper, 2014). "Moreover, inflammatory processes that are characterized by strong innate and cellular immune responses such as eosinophilia and neutrophilia or viral infection are characterized by a lack of SLURP-1." (PMID 25464511, 2014).
head and neck cancer (1 paper, 2021). A primary or metastatic malignant neoplasm affecting the head and neck. "The role of SLURP1 and CLDN10 in head and neck cancer has not been described." (PMID 34631779, 2021).
mastitis (1 paper, 2024). Inflammation of breast tissue during lactation or postpartum due to an obstructed duct or infection. "Among them, cnvr_137 contains genes such as LY6D, LYNX1, LYPD2, SLURP1,THEM6, PSCA, TSNARE1, and ARC associated to clinical mastitis in US Holstein dairy cows." (PMID 38771855, 2024).
metastatic melanoma (1 paper, 2019). A melanoma that has spread from its primary site to another anatomic site. "SLURP1:SLURP1 RNA expression is reduced in metastatic melanoma." (PMID 31068932, 2019).
pancreatic disorders (1 paper, 2018). "Re-measurement of the selected serum samples using USCN-EIA confirmed the presence of SLURP1 in the bloodstream without significant changes in patients with pancreatic disorders." (PMID 29545933, 2018).
sarcopenia (1 paper, 2023). Progressive decline in muscle mass due to aging which results in decreased functional capacity of muscles. "In contrast, SLURP1 and LCE1C expression levels were much higher in sarcopenia patients and associated with a worse prognosis and weaker immune profile." (PMID 37138756, 2023). "Among deferentially expressed genes (DEGs) and the elastic net regression model, we found five common genes (TTC39DP, SLURP1, LCE1C, PTCD2P1, and OR7E109P) that discriminated between sarcopenia patients and healthy controls with a different range." (PMID 37138756, 2023). "In addition, we analyzed the association of various immune signatures with the pre-defined top-ranked genes (TTC39DP, SLURP1, and LCE1C) that discriminated sarcopenia from healthy individuals." (PMID 37138756, 2023).
Stroke (1 paper, 2021). Sudden impairment of blood flow to a part of the brain due to occlusion or rupture of an artery to the brain. "Overall, it would be interesting to learn, what role plays SLURP-1 in the NLRP3 inflammasome induced release of IL1β as this was recently shown to be present in MC and to be attenuated by classical Chrna7 activation in a stroke model." (PMID 33815383, 2021).
tumor (22 papers, 2016 to 2026). "The exact molecular mechanisms underlying the combined effect of SLURP-1 anddoxorubicin on A431 tumor growth remain unknown." (PMID 40264586, 2025). "The protein encoded by SLURP1, a member of the Ly6/uPAR family, has anti-tumor activity." (PMID 34631779, 2021). "Tgfbr2MyeKO mice injected with Slurp1 KO or KD tumor cells showed fewer dormant lesions with only a modest effect on the total tumor lesion number (Supple fig." (PMID 40568095, 2025). "Combination with low-dose doxorubicin enhances the SLURP-1 anti-tumor activityand dramatically suppresses tumor metastasis." (PMID 40264586, 2025). "Together with previous findings in the literature, our in vivo and in vitro data support an inhibitory role of SLURP1 in tumor cell proliferation by targeting the Integrin-FAK-ERK signaling pathways." (PMID 40568095, 2025). "Recombinant IFN-γ treatment of D2A1 tumor cells increased SLURP1 mRNA in vitro under stress and nutrient-deprived conditions." (PMID 40568095, 2025). "IFN-γ in turn elevated KLF4-mediated SLURP1 production in malignant cells, which is critical to the tumor cell quiescent state through interruption of fibronectin-integrin signaling pathways." (PMID 40568095, 2025). "IFN-γ in turn induced KLF4-mediated expression of SLURP1 that is critical in promoting tumor dormant state." (PMID 40568095, 2025). "The results showed that the tumor volume and weight were significantly higher in mice subcutaneously injected with Slurp1−/− MC38 cells than in those injected with control MC38 cells." (PMID 39840525, 2025). "What features of the tumor microenvironment in Tgfbr2MyeKO mice promoted the increased expression of SLURP1 that limits tumor proliferation?" (PMID 40568095, 2025). "This is more than sufficient to act outside of the definition we have for Niche 1 radius, maintaining the quiescent state of tumor cells capable of SLURP1-mediated dormancy induction." (PMID 40568095, 2025). "The immunohistochemical staining results revealed a substantial increase in positive SLURP1 expression within PCa tumor tissue." (PMID 38686195, 2024). "Simultaneous downregulation of prooncogenic miR-221, tumor suppressive miR-203, and context-dependent tumor suppressive/pro-oncogenic miR-31 additionally highlights the dual effect of SLURP-1 in cancer cells." (PMID 37854069, 2023). "The SLURP-1 treatment significantly decreased expression of pro-oncogenic miR-221, as well as of tumor suppressive miR-203, and controversial miR-31." (PMID 37854069, 2023). "The suppression of VEGF in SLURP1-treated tumors is in parallel with published reports that support the anti-angiogenesis property of SLURP1 to reduce tumor proliferation." (PMID 37896222, 2023). "We didn’t study the chronic toxicity of SLURP-1 and Oncotag, but note that some animals died during the experiment on tumor treatment." (PMID 37854069, 2023). "To evaluate this concept, we cloned human SLURP1 into pJHL65 antigen secretion plasmid and transformed it into an attenuated Salmonella strain to deliver it directly into the tumor microenvironment." (PMID 37896222, 2023). "The designed therapeutic strain was administered to elucidate the cross-species anti-tumor potential of recombinant human SLURP1 in tumor-bearing mice." (PMID 37896222, 2023). "Despite that both SLURP-1 and Oncotag inhibited tumor growth in vivo, only Oncotag demonstrated prolonged downregulation of pro-oncogenic signaling." (PMID 37854069, 2023). "The prominent tumor reduction displays the synergistic anti-tumoral effect imposed by the treatment with SLURP1 secretion." (PMID 37896222, 2023). "Affinity extraction showed that in the xenograft tumor, Oncotag interacts only with α7-nAChR, while SLURP-1 also binds EGFR." (PMID 37854069, 2023). "Down-regulation of vascular endothelial growth factor (VEGF) in treated tumors further supports an anti-angiogenesis property of SLURP1 that helps with tumor reduction." (PMID 37896222, 2023).
tumor (continued). "Compared with normal tissues, only SLURP1 was downregulated in tumor tissues, while the expression levels of DKK1, GAST, IGHM, IL12RB2, STC2, and TNFRSF4 were upregulated in tumor tissues." (PMID 39282247, 2023). "Probably, SLURP-1 and Oncotag reprogrammed the tumor cells, which stop their proliferation and stimulated apoptosis or necrosis, and these effects persisted for several days." (PMID 37854069, 2023). "The exact mechanism of tumor cell death under the action of SLURP-1 or Oncotag requires additional investigation." (PMID 37854069, 2023). "Six of the eight mice treated with the rough ST JOL1800 strain secreting SLURP1 demonstrated a substantial reduction in tumor volume, retaining only a scar at the tumor implanted site." (PMID 37896222, 2023). "In this study, we sought to investigate the anti-tumor effect inflicted by Salmonella Typhimurium (ST) secreting SLURP1 in BALB/c mice implanted with CT26 tumors." (PMID 37896222, 2023). "Secondly, SLURP1 weakened the nicotine-mediated migration and invasion while forfeiting its own anti-tumor potential." (PMID 29545933, 2018). "The inhibitory effects of lobeline on tumor load and TAM polarization are almost completely eliminated when Slurp1‐deficient MC38 cells are subcutaneously injected into mice, suggesting that lobeline exerts an antitumor effect in a Slurp1‐dependent manner." (PMID 39840525, 2025). "Their high-level influence on the tumor's interaction with the host immune system suggests that further study of these targets could yield novel therapeutic approaches, such as enhancing anti-tumor immunity by targeting LY6D or restoring SLURP1 function." (PMID 40740240, 2025). "However, the combination with doxorubicin furtherenhanced the anti- tumor activity of SLURP-1 and dramatically suppressedmetastasis." (PMID 40264586, 2025). "Recently, wedemonstrated the high efficiency of the therapy based on the recombinantSLURP-1 in controlling SCC cell growth and metastasis in vivo.The anti-tumor effect of SLURP-1 was mediated through interaction with bothα7-nAChR and the epidermal growth factor receptor (EGFR)." (PMID 40264586, 2025). "SLURP1 has been identified as a regulator of epithelial cell growth, involvement in epithelial mesenchymal transition, programmed cell death, inflammation, and tumor development, and serves as a marker for late epithelial differentiation." (PMID 38686195, 2024). "Moreover, Salmonella secreting SLURP1 revealed a significant tumor regression in a mouse CT26 tumor model, suggesting the cross-species anticancer potential of human SLURP1." (PMID 37896222, 2023). "In addition to its anti-inflammatory role, SLURP1 is of prime interest for its anti-tumor properties supported by its ability to inhibit cell proliferation." (PMID 37896222, 2023). "Thus, increased PTEN, KLF4, and SLURP1 expression points on activation of anti-oncogenic pathways in the tumor." (PMID 37854069, 2023). "To target tumor tissues effectively while minimizing side effects, we employed a live attenuated Salmonella delivery system transformed with a plasmid for constitutive expression of recombinant SLURP1 facilitated by a beta-lactamase secretory signal." (PMID 37896222, 2023). "Thus, the simultaneous increase in CHRNA7, CERK and ITGA5 expression upon the SLURP-1 treatment illustrates the activation of pro-oncogenic intracellular signaling pathways in the tumor." (PMID 37854069, 2023). "Results of in vitro studies implied that SLURP1high-patients might be better protected against PDAC recurrence or progression through direct anti-malignant effects of SLURP1 on CHRNA7-positive tumor cells." (PMID 29545933, 2018). "At the same time, nicotine attenuates the anti-malignant activities of SLURP1 suggesting that smoking could weaken the natural anti-tumor defense provided by SLURP1." (PMID 29545933, 2018). "In contrast, down-regulation of TNFα and the tumor suppressor SERPINB5 was blocked by SLURP1." (PMID 29545933, 2018).
tumor (continued). "It is important to note that a particular subclone with the set of gene mutations (e.g. STEAP3, SLURP1 and KDM6A) within the primary tumor may have grown out or outcompeted the others and survived both chemotherapy selection and allo-HSCT treatment to evolve into the dominant clone at relapse." (PMID 26527318, 2016). "KLF4-ChiP assays in D2A1 tumor cells with KLF4 overexpression revealed that KLF4 protein was enriched at the −500~−250 and −150~+30 bp regions of the SLURP1 promoter, consistent with this motif mapping." (PMID 40568095, 2025). "In accord with these findings, both KLF4 and SLURP1 were increased in 4T1 and D2A1 tumor cells upon treatment with IFN-γ." (PMID 40568095, 2025). "Both SLURP1 and LY6D notably modulate the tumor microenvironment and immune responses, mechanisms that typically exert indirect impacts on tumor progression." (PMID 40740240, 2025). "Imaging flow cytometry revealed a higher expression of SLURP1 in CVCPos D2A1 and 4T1 dormant cells from Tgfbr2MyeKO mice as compared to tumor cells from control mice." (PMID 40568095, 2025). "TCGA database analysis revealed that LOX and IFI44 mRNA expressions were higher in ESCA tumor tissues, while IL18 and SLURP1 mRNA expressions were higher in normal tissues." (PMID 36090891, 2022). "An analysis of eight PDAC cell lines by qRT-PCR and ELISA corroborated the SLURP1-negativity of PDAC tumor cells (data not shown)." (PMID 29545933, 2018). "Most probably, the direct anti-malignant effect of SLURP1 on PDAC cells is not the only mechanism behind SLURP1-driven oncosuppression: tumor cells were not a sole source of the pancreatic CHRNA7 expression in cancerous lesions." (PMID 29545933, 2018). "Pancreatic tissue was not a source of circulating SLURP1 but contained diverse CHRNA7-expressing cells, preferentially epithelial and immune, whereas stromal stellate cells and a quarter of the tumor cells lacked CHRNA7." (PMID 29545933, 2018).